STAMBP (STAM binding protein)
Diseases named in the same sentence as STAMBP in open-access papers (continued):
Sharing a sentence is not in itself a finding about the gene and the disease.
tumor (continued). "Furthermore, investigating the single-cell expression of STAMBP, we observed predominant expression in tumor cells, with minimal expression detected in immune cells." (PMID 39242557, 2024). "The STAMBP protein level was significantly higher in tumor tissues than in adjacent normal tissues." (PMID 39242557, 2024). "The hypothesis that STAMBP mediates tumor cell growth, invasion, and migration was confirmed by the overexpression of STAMBP after gene transfection." (PMID 36434041, 2022). "Our analysis of public datasets and clinical specimens provides further support for findings suggesting that STAMBP may contribute to the tumor progression of TNBC." (PMID 36434041, 2022). "STAMBP regulates tumor metastasis by increasing EGFR stability to trigger MAPK signaling." (PMID 34102455, 2021). "The STAMBP levels were significantly elevated in the tumor tissues from NSCLC patients." (PMID 34102455, 2021). "STAMBP plays critical roles in various physiological and pathological processes, but its involvement in tumor progression remains unclear." (PMID 34102455, 2021). "Importantly, STAMBP knockdown suppressed LUAD tumor growth and metastasis by regulating the EGFR-mediated ERK activation in a xenograft mouse model." (PMID 34102455, 2021). "STAMBP appears as discrete spots distributed in a speckled pattern in the cytoplasm of tumor cells." (PMID 34102455, 2021). "We found that STAMBP expression was increased in the cytoplasm of tumor cells from LUAD patients." (PMID 34102455, 2021). "Furthermore, we investigated the effects of STAMBP on cell mobility and invasion in vitro and tumor metastasis in a xenograft mouse model in vivo." (PMID 34102455, 2021). "Thus, we hypothesized that STAMBP is likely to be involved in modulating glycolysis in PC, thereby contributing to malignant tumor progression and chemoresistance of PC cells." (PMID 39242557, 2024). "The role of ubiquitination or deubiquitination in the sorting of receptor tyrosine kinases could be different in the physiological cellular process from that in pathological status (normal cell and tumor cell), which might lead to the controversial interpretation of STAMBP on EGFR regulation." (PMID 34102455, 2021). "Immunohistochemistry confirmed that entrectinib treatment reduced the expression of STAMBP, E2F1, PDK1 and Ki-67 expression in tumor tissues." (PMID 39242557, 2024). "To probe into the functional roles of USP10, USP14, OTUB1, and STAMBP in HSC2 cells, we conducted assays to measure cell proliferation, in vitro invasion, and in vivo tumor growth." (PMID 37986681, 2023). "In this study, by performing unbiased siRNA screening, we identified STAMBP, a JAMM metalloprotease in the DUB family, as a driver of human TNBC tumor growth." (PMID 36434041, 2022). "For example, STAMBP expression is significantly increased in LAC cells and is closely related to tumour size, lymph node invasion, and tumour stage." (PMID 36276113, 2022). "In this study, our unbiased siRNA and substrate screening revealed a previously unknown role of STAMBP in TNBC: STAMBP direct removes ubiquitin from RAI14, enhancing the stability of tumor-promoting RAI14." (PMID 36434041, 2022). "Therefore, knocking down STAMBP resulted in the reduction in RAI14 protein levels and suppression of tumor growth in vitro and in vivo." (PMID 36434041, 2022). "Our findings that STAMBP knockdown promotes EGFR degradation and suppresses LUAD tumor metastasis raise the possibility that targeting STAMBP may be a promising strategy to control LUAD progression." (PMID 34102455, 2021). "To explore STAMBP expression in NSCLC tissues, we detected the STAMBP protein in paired tumor and adjacent noncancerous tissues from 24 NSCLC patients." (PMID 34102455, 2021). "STAMBP expression was detected in both the tumor and noncancerous tissues." (PMID 34102455, 2021).
tumor (continued). "The STAMBP mRNA level was markedly elevated in 8 tissues and decreased in 2 tissues out of 10 LUAD tumor tissues compared with the paired noncancerous tissues from the GEO database." (PMID 34102455, 2021).
cancer (6 papers, 2011 to 2025). A tumor composed of atypical neoplastic, often pleomorphic cells that invade other tissues. "An imbalance in STAMBP is related to specific characteristics of cancer and leads to the occurrence of malignant tumors." (PMID 39242557, 2024). "Nevertheless, specific STAMBP inhibitors need to be developed before the translation of targetable STAMBP into medical applications for cancer is realized." (PMID 36434041, 2022). "STAMBP expression was directly controlled by miR-99a-3p, and its overexpression enhanced cancer cell migration and invasion." (PMID 31795200, 2019). "Further studies are needed to analyze the molecular networks controlled by STAMBP in various cancers." (PMID 31795200, 2019). "Moreover, our findings revealed that aberrant expression of STAMBP enhanced cancer cell aggressiveness in HNSCC." (PMID 31795200, 2019). "Overexpression of STAMBP was detected in cancer lesions in HNSCC clinical specimens." (PMID 31795200, 2019). "In contrast to cancer lesions, expression of STAMBP was extremely weak in normal mucosa." (PMID 31795200, 2019). "STAMBP knockdown decreased PDK1 levels, an essential regulator of the aerobic glycolytic process, in several cancers." (PMID 39242557, 2024). "Thus, overexpression of STAMBP may promote cancer cell metastasis." (PMID 31795200, 2019).
infection (5 papers, 2020 to 2025). The state of being infected such as from the introduction of a foreign agent such as serum, vaccine, antigenic substance or organism. "The combination treatment with both TMAO and CFT073 had significant additive effects on the release of PD-L1 and STAMBP and synergistic effects on the release of CDCP1, uPA, AXIN1, MMP-10, and CD40 compared to CFT073 infection alone." (PMID 37111409, 2023). "Six out of eight proteins were significant in the longitudinal analysis for at least one effect (time [ITGB1BP2, AXIN1, MMP1, STAMBP] or condition [GH, ITGB1BP2, 4E-BP1]), suggesting their importance both during hospitalization and after infection." (PMID 36405747, 2022). "Regarding DUB expression, no apparent differences were found throughout infection in the levels of HAUSP, also called USP7, UCHL1, A20, USP10, STAMBP, and CYLD." (PMID 36851696, 2023).
neurodevelopmental disorder (1 paper, 2022). A behavioral and cognitive disorder with onset during the developmental period that involves impaired or aberrant development of intellectual, motor, or social functions. "Here, in this study, we present a Chinese patient diagnosed with a neurodevelopmental disorder carrying compound heterozygous STAMBP mutations, including a novel STAMBPG307E mutation." (PMID 36033615, 2022).
STAMBP also shares sentences with these, for which no sentence is quoted: Alzheimer disease (2 papers); lung carcinoma (2); lymph node metastasis (2); triple-negative breast carcinoma (2); allergic asthma (1); Anxiety (1); capillary malformation (1); cardiovascular disease (1); Cirrhosis (1); dental caries (1); depression (1); developmental delay (1); epilepsy (1); generalized anxiety disorder (1); head and neck cancer (1); hyperemesis gravidarum (1); inflammatory bowel disease (1); Lipedema (1); metabolic syndrome (1); narcolepsy (1); neurological disease (1); Obesity (1); postpartum depression (1); renal cell carcinoma (1); spondylolysis (1).